TIMP1 (TIMP metallopeptidase inhibitor 1)
Diseases named in the same sentence as TIMP1 in open-access papers (continued):
Sharing a sentence is not in itself a finding about the gene and the disease.
fibrosis (69 papers, 2009 to 2025). the formation of excess fibrous connective tissue in an organ or tissue in a reparative or reactive process. "Other recently validated algorithms, based on biomarkers as alpha2macroglobulin, HA, and TIMP1, are associated with better performances in discriminating between patients with advanced fibrosis or cirrhosis." (PMID 36233834, 2022). "In a CCl4-induced fibrosis rat model, Oxymatrine caused a reduction in TIMP-1 expression." (PMID 36985782, 2023). "Zhang (2015) found that salidroside significantly reduced the expression of MMP-2 and TIMP-1 mRNA and protein (p < 0.05) and attenuated the pathological changes of paraquat-induced fibrosis in rats." (PMID 38567353, 2024). "Decreased MMP-2 and MMP-9 and increased TIMP-1 were found as part of the mechanism of developed fibrosis with IL-19 KO." (PMID 37509702, 2023). "The levels of TIMP-1 were positively correlated with the level of liver inflammation and fibrosis, and the levels of MMP-1 were negatively correlated with the level of fibrosis." (PMID 32928296, 2020). "We have previously shown that two NF-κB-regulated genes, Timp1 and Opn, are significantly induced by MWCNTs in the lung during fibrosis development, and both TIMP1 and OPN play critical roles in promoting MWCNT-induced lung fibrosis." (PMID 31632276, 2019). "qRT-PCR and western blots show that Collagen I, α-SMA and TIMP1 expression were significantly increased in the fibrosis model groups, and that the increase was inhibited by quercetin." (PMID 28839277, 2017). "The median values of HA, PIIINP and TIMP-1 in patients with mild fibrosis remained highly stable over a period of 20 years." (PMID 27984583, 2016). "The interstitial collagenases MMP-2 and MMP-13 are upregulated during resolution of fibrosis, while TIMP-1 and TIMP-2 inhibit MMP activity." (PMID 26374068, 2015). "The results of our study suggest that SMAD4-shRNA is able to reduce HSC-mediate fibrogenesis via down-regulation of hepatic fibrosis markers especially col1, α-sma and TIMP1." (PMID 26468346, 2015). "In ALD subjects, the TIMP1 values increased from 105 ± 65 (F2), 205 ± 45 (F3), 872 ± 83 (F4) (P < 0.001 versus the previous fibrosis stages)." (PMID 22530132, 2012). "In HCV-infected individuals, it is important to observe the increase of TIMP1 values (ng/mL) (F0-1) 65 ± 12 to 126 ± 12 (F2); 147 ± 45 (F3); 672 ± 58 (F4) (P < 0.001 versus the previous fibrosis stages)." (PMID 22530132, 2012). "Higher values of TIMP-1 and HA were observed in both pediatric and adult patients with worse fibrosis stages." (PMID 21858035, 2011). "Furthermore, the total amount of collagen and enzyme TIMP-1 protein, the synthesis of which increases as cardiac fibrosis progresses, in the ventricular tissue was elevated by 5/6Nx treatment in ARNTL +/+ mice but not in ARNTL −/− mice." (PMID 39684718, 2024). "Urinary TNFR-1, TIMP-1, and EGF are associated with renal inflammation and fibrosis." (PMID 39229378, 2024). "This study highlights the association of α-smooth muscle actin (α-SMA), a marker of activation of hepatic stellate cells, pro-MMP2, TIMP1 and TIMP2 with severity of fibrosis in NAFLD patients, whereas pro-MMP9 is rather associated with the severity of inflammation." (PMID 37445827, 2023). "Next, the expression patterns of MMP‐2 and TIMP‐1 were examined in our fibrosis models." (PMID 32233073, 2020). "Additionally, the study confirmed, as would be expected, that the balanced expression of MMP-2 and TIMP1 was changed in both fibrosis models, but it was recovered by IH treatment." (PMID 31467486, 2019). "Similarly, for cardiac phenotypes, we identified multiple genes related to cardiac fibrosis that were up-regulated in FRDAkd mice heart, including Lgals3, Icam1 and Timp1." (PMID 29257745, 2017). "More MMP-9 and less TIMP-1 levels might have anti-fibrotic roles, and therefore be beneficial to resolve PSC-associated fibrosis." (PMID 27600527, 2016).
fibrosis (continued). "Thus, we detected MMP-9 and TIMP-1 protein expression in lung tissue in BLM-induced fibrosis." (PMID 29311918, 2017). "Additionally, increased Timp1 mRNA levels were observed in lung tissues obtained from patients with IPF in the IPF-PRO Registry cohort, where elevated levels were associated with disease severity, as measured using pulmonary function tests and imaging-based fibrosis assessment." (PMID 41323794, 2025). "As a result of this, ISO-injured mice presented with a significant reduction in LV MMP-13/TIMP-1 (by ~ 60%), MMP-9/TIMP-1 (by ~ 55%) and MMP-2/TIMP-2 (by ~ 65%) ratios at day 14 post-injury, in line with the increased LV fibrosis in these mice." (PMID 41382190, 2025). "TIMP-1 gene expression and protein are selectively increased in BALF and lung homogenate in the fibrosis model." (PMID 39596365, 2024). "As expected, the expression of collagen I, α‐Sma, and Timp1 was most profoundly down‐regulated in the Ad‐IL10 + CMC group, compared with that in the fibrosis model group and the Ad‐IL10 group." (PMID 36176604, 2022). "B1R blockade with BI 113823 inhibited the accumulation of macrophages and neutrophils in both CCl4 and BDL fibrosis livers, and reduced the expression of inflammatory mediators, B1Rs, COX-2, IL-1β, IL-6, MCP-1, MCP-3 and TIMP-1 in liver tissue." (PMID 36514072, 2022). "The protein levels of Nrf2, HO-1, α-SMA, Collagen I, Collagen III, TIMP1 and TIMP3 were markedly increased in fibrosis mice compared with control mice." (PMID 34456904, 2021). "In fibrosis mice, consistently, the expression of genes related to ECM accumulation (TIMP1, MMP3 and MMP8) were decreased and genes involved in ECM elimination (MMP2, MMP9 and MMP13) were notably upregulated after JT003 treatment." (PMID 33199780, 2020). "qPCR analysis showed a decrease in highly upregulated gene levels associated with HSC activation, namely Acta2, Col1a2, Col3a1, TIMP-1, TGF-b, and PDGFR-b, in the neratinib-treated group compared to that in the vehicle-treated fibrosis group." (PMID 32901093, 2020). "In LX2 fibrosis cells, expression of genes involved in ECM accumulation (TIMP1) and degradation (MMP9, MMP12, MMP13) were notably altered via JT003 exposure." (PMID 33199780, 2020). "TIMP1 and TIMP4 were both found to correlate inversely with suppressor of cytokine signaling 1 (SOCS1) expression in two in vitro fibrosis model systems and putatively shown to share CD63, an exosomal marker, as a binding partner in MMP-independent activities." (PMID 31765403, 2019). "OPN and VIM also exhibited higher diagnostic performance at distinguishing earlier stages of fibrosis (controls and F0 fibrosis) compared to HA and P3NP, with TIMP1." (PMID 30559459, 2018). "As MMPs are involved in mucosal fibrosis we determined the expression of tissue remodeling protease MMP-9 and the tissue inhibitor of metalloproteinases TIMP-1 in intestinal transplants by real-time PCR." (PMID 29247242, 2017). "The present results showed that the cutoff values (WFA+-M2BP, TIMP-1, HA, and FIB-4 index) to detect the advanced fibrosis stage were lower in NAFLD than in CHC." (PMID 27649152, 2016). "The fibrosis of lung was detected by assessment the level of collagen type I (COL1), metalloproteinase-9 (MMP-9) and metalloproteinases-1 (TIMP-1)." (PMID 27191651, 2016). "While the serum level of TIMP-1 was not significantly different according to severe and nonsevere fibrosis stages (p value = 0.075), we observed a tendency for this to be higher in the severe fibrosis group." (PMID 35715541, 2022). "Fibrosis involves the secretion of a series of fibrosis-related maker proteins, including collagen I, α-smooth muscle actin (α-SMA), MMP3, ECM-degrading protein and TIMP-1, which exhibit a direct role in the fibrogenesis." (PMID 34456904, 2021).
fibrosis (continued). "In adults, the extremely elevated HA value (2,225 ng/mL; result confirmed in three independent assay) and the TIMP-1 (977.5 ng/mL) and PIIINP (39.42 μg/L) uppermost values correspond to the case with stage 4 fibrosis according to modified Knodell scoring system." (PMID 21858035, 2011). "Results showed that the levels of Col1α1, Col3α1, α-SMA, MMP9 and TIMP1 were decreased while TGF-β was increased in anti-parasite group in comparison to infected group and all of them were decreased in anti-fibrosis group in comparison to both infected group and anti-parasite group." (PMID 21629648, 2011). "APN interferes with the expression of TIMP1 and TGFB1 in IBD by targeting AdipoR2, so emodin succinate monoethyl ester (ESME), an AdipoR2 agonist possibly recedes the severity of colonic fibrosis in UC and fistulae in CD by restoring balance of TIMP1 and TGFB1." (PMID 40713669, 2025). "Comparison with the ELF test, which demonstrates good accuracy in discriminating between early and advanced fibrosis was not possible as serum PIIINP and TIMP-1 dosage were not available in the two cohorts." (PMID 38679739, 2024). "We do not think that removal of PIIINP, TIMP-1, and MMP-2 by the peritoneal membrane had a significant impact on fibrosis markers plasma levels." (PMID 31141909, 2019).
glioma (65 papers, 2001 to 2025). A benign or malignant brain and spinal cord tumor that arises from glial cells (astrocytes, oligodendrocytes, ependymal cells). "The downregulation of TIMP-1 reduces glioma cell migration, which is associated with decreased tumor proliferation and increased apoptosis." (PMID 40483537, 2025). "As the tight regulatory relationship between Sp1 and TIMP1 has been identified here, we aim at investigating both molecules simultaneously as a diagnostic signature in assessing the prognosis of glioma patients." (PMID 35778451, 2022). "Our results show that high TIMP1 levels are positively associated with increased immune infiltration levels of tumor-infiltrating lymphocytes, which could migrate towards the tumor tissues in glioma, including LGG and GBM." (PMID 35778451, 2022). "TIMP-1 was one of the preferentially up-regulated genes in IDH-wild type gliomas and its higher expression indicated worse prognosis of glioma patients." (PMID 41029387, 2025). "The dysregulated expression of TIMPs has been observed in gliomas, with studies reporting reduced TIMP-1 and -2 levels correlating with higher tumor grades." (PMID 40265458, 2025). "Another study calculated significant prognostic values for four hub genes (EMP3, PDPN, TAGLN2, and TIMP1) related to m6A regulators, all with high expression in high-grade glioma, and further correlation to IDH status and transcriptome subtype." (PMID 36831575, 2023). "Quantitative PCR and immunohistochemical analysis showed that LIF, LOX, MMP9, S100A4, SRPX2, and TIMP1 were expressed at high levels in glioma, whereas SLITI1 and SMOC1 were expressed at low levels, consistent with our previous results." (PMID 36560848, 2023). "TIMP1 showed a positive correlation with glioma malignancy and its expression level was suggested as an independent predictor of glioblastoma survival." (PMID 37264314, 2023). "To fully determine the effect of TIMP1 on glioma cells, we knocked down TIMP1 in LN229 cells by transfecting specific siRNA." (PMID 35332109, 2022). "Both the RNA and protein levels of TIMP1 were decreased in response to Sp1 knockdown in glioma cells." (PMID 35778451, 2022). "Although this relationship of TIMP1 and glioma patients was confirmed by IHC, we will further validate this result in vivo." (PMID 35778451, 2022). "We evaluated the correlation of TIMP1 expression and clinicopathological characters among 180 glioma patients and 94 stomach adenocarcinoma patients." (PMID 35778451, 2022). "Our results highlighted the role of PTX3 and TIMP1 which were previously considered in glioma tumorigenesis as well as LTF as a new potential biomarker." (PMID 36153549, 2022). "After demonstrating the prognosis biomarker value of TIMP1 by IHC staining of glioma patients, we aimed to investigate the upstream transcriptional factor of TIMP1 in GBM." (PMID 35778451, 2022). "Similar to the expression pattern of CGGA mRNAseq-325, CGGA mRNAseq-693 and TCGA merged GBMLGG cohorts, CHI3L1, MSN and TIMP1 were expressed higher in high-grade gliomas than in low-grade gliomas." (PMID 35332109, 2022). "Our finding suggests a strategy for targeting TIMP1, which is short of an applicable drug in glioma patients, through inhibiting Sp1." (PMID 35778451, 2022). "TIMP1 is more highly expressed in high-grade glioma and highly correlates with m6A markers in glioma, and TIMP1 serves as a potential biomarker for prognosis." (PMID 36360294, 2022). "This study demonstrated that TIMP-1, secreted by the glioma, is an important chemoattractant of NSCs and that the TIMP-1/CD63/β1-integrin complex has an important role in inducing NSC migration." (PMID 34502227, 2021). "Here, we find two EMP3 and IGFBP2 associated genes TIMP1 and SERPINE1 are also suitable biomarkers for prognosis of glioma patients." (PMID 32328202, 2020). "The overall relationship of high TIMP1 expression with poor cancer outcome has been demonstrated in gliomas." (PMID 32547876, 2020).
glioma (continued). "Further experiments are needed to explore the precise role of TIMP1 in glioma progression, and the potential application for the novel treatment of LGGs." (PMID 32547876, 2020). "To further validate the expression of four genes in gliomas, we next detected their expressions in The Human Protein Atlas database, and the results revealed the PDPN and TIMP1 were higher expression in high-grade gliomas." (PMID 33123464, 2020). "The decision tree analysis indicates that serums ANGPT1, TIMP1, IP10, and TGFβ1 are promising combinations of targets for glioma diagnostic applications." (PMID 31861636, 2019). "Serum and plasma levels of TIMP-1 allowed the discrimination of grade IV from lower grade gliomas, and were confirmed in two additional studies." (PMID 25720744, 2015). "In situ hybridization localized TIMP-1 to glial tumour cells and also to the surrounding tumour vasculature." (PMID 11437402, 2001). "In gliomas, overexpression of TIMP1 reduces the effectiveness of topoisomerase inhibitors in GBM." (PMID 40224547, 2025). "RIPK1 was positively correlated with the expression of cyclin E1 (CCNE1), CDK2, TIMP1, N-cadherin (CHD2), and other genes implicated in glioma proliferation and invasion, whereas MLKL exhibited a weaker or negative correlation with most genes in this signature." (PMID 41429922, 2025). "Furthermore, to narrow the number down, we integrated the information of these transcriptional factors with their expression, survival analysis and correlation with TIMP1 in glioma patients." (PMID 35778451, 2022). "Moreover, we demonstrated Sp1 interact with the TIMP1 promoter to upregulate its expression in glioma cells." (PMID 35778451, 2022). "It was previously reported that treatment with THC or CBD down-regulated the expression of major proteins associated with glioma tumor migration, in particular MMP-2, MMP-9, TIMP-4, and TIMP-1, even at low concentrations, which were insufficient to induce cell apoptosis." (PMID 35454080, 2022). "TIMP1 plays an important role in the IDH wild type gliomas, which could promote the survival of cancer cells by negatively regulating the adaptive immune response." (PMID 34093830, 2021). "The study found that PDPN and TIMP1 can be used as prognostic factors for glioma." (PMID 34900988, 2021). "Moreover, we also found PDPN and TIMP1 were highly expressed in high-grade glioma from The Human Protein Atlas database and both of them were correlated with m6A and immune cell marker in glioma tissue samples." (PMID 33123464, 2020). "Additionally, SERPINA5 and TIMP1 mRNA expression were significantly increased with the increase of glioma grades in both TCGA LGG dataset and CGGA dataset." (PMID 32547876, 2020). "Thus, further studies should be performed to establish the exact mechanisms of TIMP1 in the tumor microenvironment and its pro-tumorigenic function in gliomas." (PMID 32547876, 2020). "Collectively, these results suggested that TIMP1 may be an important biomarker in glioma patient fluids and target for designing therapy." (PMID 32547876, 2020). "Furthermore, PDPN and TIMP1 were confirmed that they were higher expression in high-grade glioma and knockdown their expression decreased the glioma cell proliferation in vitro." (PMID 33123464, 2020). "In addition, we found inhibition of TIMP-1, a stromal factor with multiple functions, whose over expression correlates with aggressive clinical behavior of a spectrum of tumors, gliomas included." (PMID 24204703, 2013). "Moreover, the complex interplay between MMPs and TIMPs adds another layer of regulatory complexity, where the balance between MMP-9 and TIMP-1 has been shown to influence glioma invasiveness, with higher TIMP-1 levels correlating with reduced MMP-9 activity and, consequently, reduced tumor invasion." (PMID 40265458, 2025). "TIMP1, an inhibitor of MMPs, may contribute to glioma malignancy when upregulated." (PMID 36334237, 2023).